BCL2 (BCL2 apoptosis regulator)
Diseases named in the same sentence as BCL2 in open-access papers (continued):
Sharing a sentence is not in itself a finding about the gene and the disease.
cervical carcinoma (continued). "Overexpression of PRDX1 significantly promoted proliferation and inhibited apoptosis by increasing the expression of Nanog, proliferating cell nuclear antigen (PCNA), B-cell lymphoma-2 (Bcl-2) and downregulating the expression of Bcl2-associated X protein (BAX) in SiHa cervical cancer cells." (PMID 31956363, 2020). "Studies have shown that abnormal expressions of signaling molecules including phosphatidylinositol 3-kinase (PI3K), epidermal growth factor receptor (EGF-R), β-catenin, extracellular signal-regulated kinase (ERK) and Bcl-2 played significant parts in cervical cancer progression." (PMID 31255182, 2019). "Moreover, western blot revealed that the expression levels of anti-apoptotic Bcl-2 were decreased while pro-apoptotic Bax and Cleaved caspase-3 were increased significantly in cervical cancer cells derived CSCs after zoledronic acid treatment." (PMID 30791957, 2019). "In addition, si-circCLK3 decreased Bcl-2 and Ki-67 expression and overexpression of circCLK3 increased Bcl-2 and Ki-67 expression, indicating that circCLK3 promotes cell proliferation of cervical cancer." (PMID 31831728, 2019). "In addition, betulin can regulate expressions of Bcl-2 and Bax in gastric and cervical cancer cells." (PMID 31887988, 2019). "Another novel finding of this study is that Bcl-2 could be a major resistance factor of ABC294640 in cervical carcinoma cells." (PMID 29416779, 2018). "BH3-mimetics that inhibit specific BCL-2 anti-apoptotic proteins may hold encouraging treatment outcomes for cervical cancer management." (PMID 29580266, 2018). "Hence, the aim of this pilot study is to investigate the sensitivity of cervical cancer cell lines to combination of two BH3-mimetics namely ABT-263 which selectively inhibits BCL-2, BCL-XL and BCL-w and A-1210477, a selective MCL-1 inhibitor." (PMID 29580266, 2018). "Future work should also investigate the expression of the BCL-2 proteins and caspases before and after treatment so that a mechanism for induction of apoptosis in cervical cancer cell lines by the drug combination could be established." (PMID 29580266, 2018). "In addition, ethanol extract of B. batryticatus also had significant anti-cervical cancer activity against HeLa cells with IC50 value of 1.7 mg/mL by inducing apoptosis via the regulation of the Bcl-2 and Bax." (PMID 29053625, 2017). "In our study, the level of CytoC was increased 4.4 times after treatment with 20 μM CAPE-pNO2, and the up-regulation of Bax and down-regulation of Bcl-2 suggested that CAPE-pNO2 induced cervical cancer cell apoptosis by affecting the expression of Bcl-2 family proteins." (PMID 29212221, 2017). "All of these results in our study suggested that miR-34a and miR-206 might be involved in the progression and prognosis of cervical cancer through targeting Bcl2 and c-Met." (PMID 28615991, 2017). "c-Met and Bcl2 up-regulated promote cervical cancer progress." (PMID 28615991, 2017). "The increase in Bcl-2/Bax ratio inhibits the apoptosis of human cervical cancer cells." (PMID 28070169, 2017). "In our research, we found miR-34a down-regulated in cervical cancer tissue and it might be involved in the metastasis and progression in patients with cervical cancer through targeting Bcl2 and c-Met which have been confirmed as targets of miR-34a." (PMID 28615991, 2017). "In this study, we detect the expression of miR-34a and miR-206 in the cervical cancer tissue through quantificational real-time polymerase chain reaction (qRT-PCR) assay, and the expression of Bcl2 and c-Met from cervical cancer tissue were detected by immunohistochemistry." (PMID 28615991, 2017). "In this study, we found that the aberrant expressed microRNAs, miR-34a and miR-206, may play crucial roles through targeting Bcl2 and c-Met genes in cervical cancer tissue." (PMID 28615991, 2017).
cervical carcinoma (continued). "Similarly, expression levels of leptin correlated positively with the grades of cervical carcinoma as well as expression of c-myc and bcl-2, indicating the regulatory roles of leptin in cell proliferation and apoptosis in cervical cancer cells." (PMID 27185268, 2016). "Therefore, the in vitro, as well as the ex vivo data strongly suggest that Bcl-2 is a promising therapeutic target for the treatment of cervical cancer." (PMID 26474854, 2015). "Silencing of Bcl-2 upregulated Beclin-1 expression in both cervical cancer cell lines." (PMID 26474854, 2015). "Neoechinulin A displayed cytotoxic effects against human cervical carcinoma HeLa cells, and its induction of apoptosis in HeLa cells occurred through the down-regulation of Bcl-2 expression, the up-regulation of Bax expression, and the activation of the caspase-3 pathway." (PMID 26090846, 2015). "Analysis of cervical pre-malignant and malignant tissue revealed that Bcl-2 protein expression was significantly increased in cervical carcinoma tissue samples and suggests that the malignant state requires such an alteration in order to maintain the malignant phenotype." (PMID 26474854, 2015). "In vitro treatment of HeLa cells with GA leads to the inhibition of cell proliferation, an exponential increase in apoptosis and a reduction in Bcl-2 expression, indicating that Hsp90 has an important role in the proliferation and apoptosis of cervical carcinoma cells by regulating Bcl-2 expression." (PMID 25289059, 2014). "GA may inhibit the binding of Hsp90 to Bcl-2, promoting apoptosis and mediating the signaling pathways for the apoptosis of cervical carcinoma cells." (PMID 25289059, 2014). "Therefore, GSPs induced the apoptosis of cervical cancer cells through the down-regulation of Bcl-2 and the up-regulation of Bak-1." (PMID 25187959, 2014). "In studies on human cervical cancer SiHa cells, taurine was observed to inhibit cell proliferation and induce apoptosis, affecting the expression of proteins such as Mammalian Sterile 20-like Kinase 1 (MST1), Bcl-2-associated X protein (Bax), and B-cell lymphoma 2 (Bcl-2)." (PMID 41322274, 2025). "In contrast, eleutheroside B can significantly increase Bax expression, decrease Bcl-2 expression, and increase the Bax/Bcl-2 ratio to increase cytoplasmic cyt c and downregulate anti-apoptotic protein survival, implicating the mitochondrial apoptotic pathway in cervical cancer." (PMID 38711526, 2024). "STAT3 may upregulate the autophagy level of cervical cancer cells through the Bcl2-Beclin1 axis." (PMID 35057825, 2022). "Thus, the down-regulated expression of CD34 and Bcl-2 may reflect an efficient NACT response in cervical cancer." (PMID 33392721, 2021). "Despite synergistically enhancing the effect of paclitaxel against paclitaxel-resistant cervical cancer cells, alkaloids from Piper nigrum could also enhance mitomycin-C (MMC) therapy of human cervical cancer through suppression of Bcl-2 signaling pathway via inactivation of STAT3/NF-κB." (PMID 34395473, 2021). "Cisplatin may enhance the interaction between HMGA2 and serine‐threonine kinase casein kinase II A1, thereby causing enhancement of HMGA2 phosphorylation in a time‐ and dose‐dependent manner, which in turn affects the bcl‐2/bax pathway and the resistance of cervical cancer cells to cisplatin." (PMID 34115920, 2021). "When both cervical cancer cells were treated with 2.5, 5.0 and 10.0 ng/ml of Colchicine for 48 h, the protein expression levels of Bax, cleaved caspase 3 and cytochrome c in cytosolic fraction were increased in a dose-dependent manner, whereas the Bcl-2 protein expression was in the opposite manner." (PMID 32163135, 2020).
cervical carcinoma (continued). "Bcl-2 inhibition could further sensitize ABC294640's activity against cervical carcinoma cells." (PMID 29416779, 2018). "Multivariate Cox proportional hazards model for all variables that were statistically significant in the univariate analysis demonstrated that high expression of Bcl2 and c-Met might be independent prognostic factors for the overall survival of the patients suffering from cervical cancer." (PMID 28615991, 2017). "The authors demonstrated increased expression of TLR-8 in HeLa cells and in cervical cancer tissue from patients; in this study also was evaluated the correlation between TLR-8 expression and two genes associated to the pathogenesis of cancer like Bcl-2 and VEGF." (PMID 25622528, 2015). "Thus, the expression of Bcl-2 and Bak-1 was examined by western blotting to determine whether these two proteins are involved in the induction of cervical cancer cell apoptosis by GSPs." (PMID 25187959, 2014). "In cervical cancer, miR-143 may promote apoptosis and inhibit tumor formation by targeting Bcl-2." (PMID 24774218, 2014). "There was a significant downregulation of BCL-2 (p < 0.01), MDM2 (p < 0.0001), and CDK2 (p < 0.01) expression levels in the L. cornuta-treated cervical cancer cells compared to the NC." (PMID 39005932, 2024). "The combination treatment of cervical cancer cells with crocin and cisplatin promotes antiproliferation and apoptosis by downregulating miR-365a-3p, an upregulator of BAX and BCL2." (PMID 36612314, 2023). "Therefore, the inhibitory effect of FA on the growth of transplanted tumors of human cervical cancer in nude mice may be realized by upregulating miR-34a, thus inhibiting the expression of its target gene Bcl-2, initiating the apoptotic pathway and promoting cell apoptosis." (PMID 37202657, 2023). "Studies have shown that autophagy can be induced by regulating targeted genes (such as Bcl-2, THBS2) and pathways (such as Wnt signaling pathway) to promote apoptosis in cervical cancer cell." (PMID 37740231, 2023). "Thus, I. viscosa extracts showed significant cytotoxic effects against cervical cancer cell lines through the inhibition of proliferation and induction of apoptosis involving a mitochondria-mediated signaling pathway by pro-caspase activation, BCL-2 expression, and PARP cleavage." (PMID 36359261, 2022). "In a previous study, a proteomic panel consisting of BCL-2, HER2, CD133, CAIX, and ERCC1 significantly predicted survival in patients with locally advanced cervical cancer." (PMID 34350111, 2021). "In the present study, we investigated the prognostic significance of BCL-2, HER2, CD133, CAIX, and ERCC1 expression in early-stage cervical cancer because they were prognostic factors in locally advanced cervical cancer." (PMID 34350111, 2021). "In cervical cancer, the activated JAK/STAT signaling pathway by Bcl-2 promotes cell viability, migration, and invasion." (PMID 33671013, 2021). "BCL-2, HER2, CD133, CAIX, and ERCC1 expression was determined by the immunohistochemical staining of 336 cervical cancer tissue microarrays." (PMID 34350111, 2021). "The most prominent targets of these miRs are PTEN, CRK proto-oncogene, adaptor protein (CRK), SOD2, TXNIP IGF1R, BCL2 apoptosis regulator (BCL2), and FOXK1, which play a crucial role in cervical cancer progression." (PMID 33802524, 2021). "The present study focused on targeting the Bcl-2–Beclin 1 complex, which is known as the key regulator of PCD, to deeply elucidate the molecular mechanism of RCE-4 against cervical cancer." (PMID 34830185, 2021).
cervical carcinoma (continued). "Consistent with the previous findings, our study demonstrated that overexpression of PRDX1 significantly promotes cervical cancer cell proliferation, and enhanced the expression of Nanog, PCNA and Bcl-2 and decreased the expression of BAX." (PMID 31956363, 2020). "The level of Bcl-2, MMP-2, MMP-9, Fascin, and Erzin expression was significantly upregulated in cervical cancer cells with LGALS1 overexpression, while converse results were obtained in LGALS1 knockdown cancer cells." (PMID 32047564, 2020). "We established Bcl-2 overexpressing stable clones of endogenous Bcl-2-free cells using MDCK and two other cervical cancer cell lines (SiHa and HeLa)." (PMID 29531834, 2018). "Collectively, high expression of survivin and BCL-2 and low expression of KAI 1 were reported to promote cervical cancer progression and metastasis." (PMID 29580266, 2018). "Bcl-2 and Caspase 3 expression were examined to evaluate the potential role of HMGA2 in cervical carcinogenesis in SiHa, CaSki, and S12 cervical cancer cells." (PMID 29487700, 2018). "There are number of studies which report that BCL-2 anti-apoptotic proteins (e.g. BCL-2, BCL-XL, and MCL-1) are highly expressed in cervical cancer tissues compared to the normal cervical epithelia." (PMID 29580266, 2018). "Besides Bcl2 and c-Met, which were significantly up-regulated in cervical cancer in our study, other target genes of miR-34 and miR-206 may also play crucial roles in the progression of cervical cancer tissue and which is the dominant role remain to be definite." (PMID 28615991, 2017). "PA-MSHA induced BAD and BAX and inhibited BCL-2, suggesting that PA-MSHA promotes apoptosis in cervical cancer cells by increasing the expression of pro-apoptotic genes and reducing the expression of anti-apoptotic genes." (PMID 27206797, 2016). "This compound is pro-apoptotic in human HeLa cervix carcinoma and SW1353 chondrosarcoma cells through the activation of caspase-3, caspase-8 and caspase-9, the down-regulation of Bcl-2, the up-regulation of Bax and the release of cytochrome c (cyt c)." (PMID 26090846, 2015). "As a result, since the increase in caspase‐3 and 9 activities and the Bax/Bcl‐2 ratio is considered an apoptotic marker, it was concluded that CHD has significant importance in cervical cancer research as a cytotoxic and apoptotic effective extract with its low IC50 value." (PMID 40666823, 2025). "By activating the ROS/JNK pathway, promoting Bcl-2 phosphorylation, leading to the dissociation of Bcl-2 from BECN1, and inducing autophagy, enhanced autophagy lysosome formation can significantly downregulate cervical cancer cell HPV E6 and E7 expression levels and effectively inhibit their growth." (PMID 38711526, 2024). "Supporting our results, previous studies have shown that AM induces apoptotic cell death by increasing Bax and cytochrome c release, decreasing Bcl-2, and activating caspase-9/caspase-3 cascade as well as the ASKI/MKK3/6/p38 signaling pathway in HeLa and SiHa cervical cancer cells." (PMID 36769377, 2023). "Although the BAX/BCL-2 ratio remained constant, these findings highlight the potential of SAF as a promising candidate for further study in the development of cancer therapies, particularly targeting cervical cancer HeLa cells." (PMID 37598145, 2023). "In addition, DSF/Cu inhibited the expression of bcl2 and ABCG2 protein in two cervical cancer cell lines." (PMID 35534815, 2022). "It was confirmed that the autophagy level of cervical cancer cells increased after the downregulation of STAT3, which may play a role through the Bcl2-Beclin1 axis." (PMID 35057825, 2022).